STAG2 (STAG2 cohesin complex component)
Diseases named in the same sentence as STAG2 in open-access papers (continued):
Sharing a sentence is not in itself a finding about the gene and the disease.
thyroid cancer (2 papers, 2023 to 2025). "STAG2-deficient thyroid cancer cells exhibit more lower glutamine availability due to decreased levels of c-Myc." (PMID 37479689, 2023). "We further evaluate the therapeutic potential of BPTES in STAG2-deficient thyroid cancers using xenograft tumor model." (PMID 37479689, 2023). "To elucidate the mechanism of STAG2-deficient thyroid cancer cells being more sensitive to glutamine deprivation, we first determined the impact of STAG2 knockdown on the expression of glutamine transporter SLC1A5 and glutaminases GLS and GLS2, which are essential for glutamine metabolism." (PMID 37479689, 2023). "Thus, targeting glutamine metabolism will provide an alternative therapeutic strategy for STAG2-deficient thyroid cancers." (PMID 37479689, 2023). "However, whether targeting ANSN may be an alternative therapeutic strategy for STAG2-deficient thyroid cancer cells need be further explored." (PMID 37479689, 2023). "Specifically, ERK cascade is overactivated when STAG2 is down-regulated in thyroid cancer cells, followed with suppression of HER3 transcription and RAS signaling to promote protein degradation of c-Myc via AKT/GSK3β signaling pathway." (PMID 37479689, 2023). "In the present study, we found that STAG2 was frequently down-regulated in thyroid cancers compared with control subjects." (PMID 37479689, 2023). "Surprisingly, we find that STAG2 knockdown makes BRAF-mutant thyroid cancer cells more sensitive to glutamine deprivation or glutaminase inhibitor via the ERK/AKT/GSK3β/c-Myc feedback axis." (PMID 37479689, 2023). "Our data, taken together, demonstrate that STAG2 inactivation reprograms glutamine metabolism of BRAF-mutant thyroid cancer cells, thereby improving their cellular response to glutaminase inhibitor." (PMID 37479689, 2023). "To determine whether STAG2 inactivation enhancing the response of thyroid cancer cells to glutamine deprivation was mediated by c-Myc, we ectopically expressed c-Myc in STAG2-knockdown thyroid cancer cells." (PMID 37479689, 2023). "Thus, we attempted to determine whether STAG2 inactivation affected glucose or glutamine metabolism of BRAF-mutant thyroid cancer cells." (PMID 37479689, 2023). "Thus, we speculate that c-Myc may act as a key player in STAG2 inactivation-mediated reprogramming of glutamine metabolism in BRAF-mutant thyroid cancer cells." (PMID 37479689, 2023). "This approach identified significant dependencies on key genes/proteins such as KRAS, NRAS, PABPC1, PPP2R1A, STAG2, and BRAF in thyroid cancer cell lines, underscoring their potential as critical therapeutic targets." (PMID 40297138, 2025). "Our data showed that STAG2 knockdown not only made BRAF-mutant thyroid cancer cells more dependent on glutamine rather than glucose, but also rendered them more sensitive to glutaminase inhibitor." (PMID 37479689, 2023). "Mechanistically, knocking down STAG2 in BRAF-mutant thyroid cancer cells decreases the protein stability of c-Myc via the ERK/AKT/GSK3β feedback pathway, thereby impairing glutamine metabolism of thyroid cancer cells by down-regulating its downstream targets such as SCL1A5, GLS and GLS2." (PMID 37479689, 2023). "In summary, the present study demonstrates that, although STAG2 inactivation activates ERK signaling, it does not affect cell proliferation and colony formation of BRAF-mutant thyroid cancer cells as well as their response to MEK inhibitor." (PMID 37479689, 2023).
uterine cancer (2 papers, 2015 to 2020). Primary or metastatic malignant neoplasm involving the uterine corpus and/or the cervix. "Moreover, we provided statistical evidence that hypermutation of cancer driver genes on inactive X chromosomes is a general feature in female cancer genomes and found a putative X-inactive specific gene STAG2 in uterine cancer." (PMID 26352260, 2015). "We found that the patients harboring DDX3X or STAG2 nonsynonymous mutations have a higher genome mutation density in uterine cancer during the genome-wide mutation rate analysis." (PMID 26352260, 2015).
chronic myelomonocytic leukemia (1 paper, 2016). A myelodysplastic/myeloproliferative neoplasm which is characterized by persistent monocytosis, absence of a Philadelphia chromosome and BCR/ABL fusion gene, fewer than 20 percent blasts in the bone marrow and blood, myelodysplasia, and absence of PDGFRA or PDGFRB rearrangement. "STAG2 has been reported in myeloid diseases, such as MDS, AML and chronic myelomonocytic leukemia, and encodes components of the cohesion complex." (PMID 27959900, 2016).
colorectal adenocarcinoma (1 paper, 2023). The most common type of colorectal carcinoma. "To confirm this finding, we collected a colorectal adenocarcinoma patient cohort from our institute and examined the expression of STAG2 in tumor tissues." (PMID 37985839, 2023). "Importantly, colorectal adenocarcinoma (COADREAD) patients with high STAG2 expression had significantly worse overall survival than those with low STAG2 expression." (PMID 37985839, 2023). "Moreover, in xenografts of DLD‐1 colorectal adenocarcinoma cells transduced with sgRNAs targeting STAG2 or control (non‐targeted sgRNA), knockout of STAG2 significantly inhibited tumor growth with ATMi treatment, as measured by tumor volume or tumor mass." (PMID 37985839, 2023).
congenital heart disease (1 paper, 2025). A heart disease that is present at birth. "Emerging data indicate that STAG2 variants can lead to both syndromic and isolated presentations of congenital heart disease, with truncating mutations producing dosage-sensitive phenotypes and variable expressivity." (PMID 41300816, 2025). "Recognition of such presentations supports the inclusion of STAG2 in the differential diagnosis for complex congenital heart disease and underscores the diagnostic utility of rapid trio exome sequencing in neonatal care." (PMID 41300816, 2025).
esophageal adenocarcinoma (1 paper, 2022). A malignant tumor with glandular differentiation arising predominantly from Barrett mucosa in the lower third of the esophagus. "Survival analysis demonstrated that high STAG2 expression was significantly associated with poorer overall survival (OS) and progression-free survival (PFS) in esophageal adenocarcinoma (EAC)." (PMID 35371307, 2022).
gliosarcoma (1 paper, 2021). A rare histological variant of glioblastoma (WHO grade IV) characterized by a biphasic tissue pattern with alternating areas displaying glial and mesenchymal differentiation (WHO). "Other mutations seen in high frequency in this particular analysis of gliosarcoma include TERT promoter, CDK2NB, RB1, and STAG2." (PMID 34504233, 2021).
glutamine metabolic disorder (1 paper, 2023). "Considering that asparagine synthetase (ASNS) is a compensation in glutamine metabolic disorder, we thus determined the effect of STAG2 knockdown on ASNS expression, and found increased expression of ASNS in STAG2-knockdown cells, further highlighting the metabolic plasticity of cancer cells." (PMID 37479689, 2023).
leukocytosis (1 paper, 2021). "In addition, we observed normalization of leukocytosis, monocytosis, and thrombocytopenia in Tet2/Stag2-mutant mice treated with talazoparib, which was associated with increased numbers of megakaryocytes on blinded review (P = 0.007)." (PMID 33351783, 2021).
lymph node metastasis (1 paper, 2016). "In patient 1, tumour 3 (T3) and a lymph node metastasis shared 52 (26%) of 198 mutations, including a KRAS (p.G12V) mutation and a STAG2 nonsense mutation (p.R305X), suggesting that the tumour metastasized to the lymph node." (PMID 27767028, 2016).
metastatic melanoma (1 paper, 2022). A melanoma that has spread from its primary site to another anatomic site. "We then examined the association of STAG2 expression with response to PD-1 immune checkpoint blockade in a large cohort of metastatic melanoma patients." (PMID 35388001, 2022).
Miscarriage (1 paper, 2022). A pregnancy that ends at a stage in which the fetus is incapable of surviving on its own, defined as the spontaneous loss of a fetus before the 22th week of pregnancy. "Among the prioritized genes we found STAG2 coding for the cohesin complex subunit, for which inactivation in mouse is lethal, and TLE4 a target of Notch and Wnt, physically interacting with a region on chromosome 9 associated to miscarriages." (PMID 35132093, 2022).
myeloproliferative neoplasm (1 paper, 2021). A clonal hematopoietic stem cell disorder, characterized by proliferation in the bone marrow of one or more of the myeloid (i.e., granulocytic, erythroid, megakaryocytic, and mast cell) lineages. "In EZH2-mutated patients with myelodysplastic or myeloproliferative neoplasms, the most common co-mutations were in ASXL1 (100%), NRAS, RUNX1, and STAG2 (29% each)." (PMID 33845873, 2021).
papillary thyroid cancers (1 paper, 2023). "We first analyzed STAG2 expression in papillary thyroid cancers (PTCs) from The Cancer Genome Atlas (TCGA) database and Gene Expression Omnibus (GEO) database (GSE33630)." (PMID 37479689, 2023).
pulmonary atresia (1 paper, 2025). "The current case is distinguished by a severe conotruncal defect (pulmonary atresia, double-outlet right ventricle, large VSD, and PDA), which has not been previously reported in STAG2 MKMS, thereby expanding the recognized cardiac phenotype." (PMID 41300816, 2025).
soft tissue sarcoma (1 paper, 2020). A malignant neoplasm arising from muscle tissue, adipose tissue, blood vessels, fibrous tissue, or other supportive tissues excluding the bones. "While the literature on mutational changes in pleomorphic sarcomas is sparse, a recent study on human soft tissue sarcomas found only occasional mutations in the cohesin complex, suggesting that STAG2 mutation is not a common mechanism for the development of pleomorphic sarcomas." (PMID 31898537, 2020).
Strabismus (1 paper, 2025). A misalignment of the eyes so that the visual axes deviate from bifoveal fixation. "While some studies in STAG2-related disease have reported ocular abnormalities such as strabismus, there is a paucity of detailed retinal phenotyping." (PMID 40943870, 2025).
thyroid (1 paper, 2016). "SPOP, NF1, BRIP, CNOT1, KMT2C and STAG2 mutations previously identified in PTC might be involved in thyroid tumorigenesis in a type-nonspecific manner." (PMID 27626165, 2016).
transitional cell carcinoma (1 paper, 2021). A malignant neoplasm arising from the transitional epithelium, usually affecting the urinary bladder, ureter, or renal pelvis. "Despite the detailed mechanism of STAG2 leading to the pathogenesis of transitional cell carcinoma is still not known, the high-frequency recurrent mutant gene is indeed a new pathway associated with transitional cell carcinoma in the SCCS process of transitional cell bladder cancer." (PMID 34094968, 2021).
trisomy (1 paper, 2024). A chromosomal abnormality consisting of the presence of one chromosome in addition to the normal diploid number. "Currently, our data does not allow us to predict the order of STAG2 and trisomy 8 acquisition, or whether trisomy 8 may affect response to DNA damage repair inhibitors or replication fork stressors, such as PARP inhibitors or hydroxyurea." (PMID 39033241, 2024).
trisomy 21 (1 paper, 2022). A chromosomal disorder consisting of the presence of an extra chromosome 21. "Thus, using CRISPR/Cas9 gene editing of trisomy 21 iPSCs, we provide experimental evidence for the co-operation between trisomy 21, GATA1s, and STAG2 knockout." (PMID 35203280, 2022).
uterine corpus endometrial carcinoma (1 paper, 2023). A endometrial carcinoma (disease) that involves the body of uterus. "Among the tumor types with a high frequency of STAG2 mutation, STAG2‐mutant uterine corpus endometrial carcinomas (UCEC) showed a significant increase in KMT5A expression compared to STAG2‐proficient UCECs." (PMID 37985839, 2023).
uterine tumors (1 paper, 2015). "Additionally, the average number of mutations per Mb for 26 STAG2 mutated uterine tumors (144.5 ± 26.0) is significantly higher than that for STAG2 WT samples (10.2 ± 2.2, q = 1.9 × 10−10)." (PMID 26352260, 2015).
cancer (98 papers, 2013 to 2026). A tumor composed of atypical neoplastic, often pleomorphic cells that invade other tissues. "Somatic pathogenetic variants in cohesin genes, such as STAG2, have been associated with cancer, but their contribution to brain tumorigenesis is unclear." (PMID 41502392, 2026). "Although STAG2 genetic changes are more commonly linked to cancer, some STAG1 variants have been implicated in tumorigenesis by affecting chromatin architecture and leading to oncogenic gene misregulation." (PMID 40361893, 2025). "Genes encoding cohesin subunits are mutated in a wide range of human cancers, with STAG2 being the most commonly mutated subunit." (PMID 40642059, 2025). "The STAG2 tumor suppressor gene is commonly inactivated by mutations in a wide range of common cancer types." (PMID 41091719, 2025). "STAG2 mutations are associated with DNA damage repair defects and aneuploidy in numerous cancer types." (PMID 38030788, 2024). "Mutation in STAG2 disrupts the cohesin complex, affecting cell division and genomic stability, which is crucial in the pathogenesis of several cancers including sAML." (PMID 39135995, 2024). "Within the nucleus, NIDP2 localized to the host chromatin and interacted with the tumor suppressor STAG2, shedding light on potential mechanisms underlying host cell transformation of cancer-related pathways." (PMID 38747635, 2024). "We confirm synthetic lethal relationships between DDX11 and the tumor suppressor cohesin subunit STAG2, which is frequently mutated in several cancer types and the kinase HASPIN." (PMID 38478595, 2024). "STAG1 represents the vulnerability of cancer cells that carry mutations in the major emerging tumor suppressor STAG2 in different cancer environments." (PMID 39390002, 2024). "Conversely, overexpression of STAG2 in the cancer cell line with an inactivating mutation of STAG2 (i.e., UMUC3) resulted in PARPi resistance." (PMID 37985839, 2023). "STAG2 emerges as a gene subject to frequent mutations in the context of human cancers, exhibiting a noteworthy prevalence of mutational events alongside concurrent loss of expression." (PMID 37985839, 2023). "To this end, we meticulously conducted an analysis of STAG2 mutation data within comprehensive pan‐cancer datasets procured from TCGA." (PMID 37985839, 2023). "Aligned with our prior assertion, STAG2 emerges as a recurrently mutated gene across diverse cancer types, often accompanied by concurrent loss of expression." (PMID 37985839, 2023). "STAG2 (stromal antigen 2), a redundant subunit of cohesin complex, is the most frequently mutated cohesin complex component in several types of cancers." (PMID 35203280, 2022). "Somatic LoF mutations of STAG2 have been frequently observed in several types of human cancers; more recently, germline variants have been associated with MKMS and HPE." (PMID 35887945, 2022). "The synthetic lethal interaction between STAG2-mutant cells and DNA damage repair genes was common to other cancer types carrying STAG2 mutation." (PMID 35065680, 2022). "Numerous studies have demonstrated that STAG2 mutation is a common and important event in the pathogenesis of diverse human cancers." (PMID 36016405, 2022). "Recent exome sequencing revealed that the STAG2 protein of cohesin is frequently mutated in cancers." (PMID 36589746, 2022). "As a consequence, the role of STAG2 in triggering the aneuploidy associated cancer is still debated." (PMID 35287703, 2022). "Mutations in STAG1 and STAG2 have been identified in human developmental syndromes and STAG2 is frequently mutated in cancer." (PMID 36424654, 2022). "STAG2 is a frequent target of inactivating mutations in human cancers, which are only partially compensated for by its paralogue, STAG1." (PMID 35287703, 2022). "More recently, dropout CRISPR-Cas9 screens in isogenic cancer cells have been conducted to identify genetic synthetic lethal targets with STAG2 mutations." (PMID 34202641, 2021).